TRBV9 (T cell receptor beta variable 9)
Description:
V region of the variable domain of T cell receptor (TR) beta chain that participates in the antigen recognition. Alpha-beta T cell receptors are antigen specific receptors which are essential to the immune response and are present on the cell surface of T lymphocytes. Recognize peptide-major histocompatibility (MH) (pMH) complexes that are displayed by antigen presenting cells (APC), a prerequisite for efficient T cell adaptive immunity against pathogens. Binding of alpha-beta TR to pMH complex initiates TR-CD3 clustering on the cell surface and intracellular activation of LCK that phosphorylates the ITAM motifs of CD3G, CD3D, CD3E and CD247 enabling the recruitment of ZAP70. In turn ZAP70 phosphorylates LAT, which recruits numerous signaling molecules to form the LAT signalosome. The LAT signalosome propagates signal branching to three major signaling pathways, the calcium, the mitogen-activated protein kinase (MAPK) kinase and the nuclear factor NF-kappa-B (NF-kB) pathways, leading to the mobilization of transcription factors that are critical for gene expression and essential for T cell growth and differentiation. The T cell repertoire is generated in the thymus, by V-(D)-J rearrangement. This repertoire is then shaped by intrathymic selection events to generate a peripheral T cell pool of self-MH restricted, non-autoaggressive T cells. Post-thymic interaction of alpha-beta TR with the pMH complexes shapes TR structural and functional avidity.
Synonyms: TCRBV1S1A1N1; TCRBV9S1
Gene: T-cell receptor variable (V) gene on chromosome 7 (142,391,891 to 142,392,412, forward strand). Ensembl gene ENSG00000211716.
Subcellular location: Cell membrane
Gene Ontology:
Biological process: cell surface receptor signaling pathway
Cellular component: plasma membrane
Homologues: Orthologues: macaque TRBV9 (75% identical), dog TRBV9 (69% identical), pig TRBV9 (65% identical). Paralogues in human: TRBV5-5 (66% identical), TRBV5-1 (63% identical), TRBV5-6 (62% identical), TRBV5-7 (61% identical), TRBV5-3 (60% identical), TRBV5-4 (60% identical), TRBV13 (59% identical), TRBV7-9 (48% identical), TRBV3-1 (46% identical), TRBV7-2 (46% identical), TRBV11-3 (46% identical), TRBV12-4 (45% identical), and 39 more.
Diseases named in the same sentence as TRBV9 in open-access papers:
TRBV9 is named in the same sentence as 13 diseases in open-access papers, as found by Europe PMC text mining. Sharing a sentence is not in itself a finding about the gene and the disease. The quoted sentences say what the papers report.
ankylosing spondylitis (3 papers, 2023 to 2025). An autoimmune chronic inflammatory disorder characterized by inflammation in the vertebral joints of the spine and sacroiliac joints. "Remarkably, although the overall frequency of TRBV9+ T cells in peripheral blood remained extremely low, deep targeted profiling of the TRBV9 TCR repertoire revealed the reappearance of ankylosing spondylitis-associated CDR3 motifs at this time (red arrow)." (PMID 37872223, 2023). "Following successful validation in non-human primate models, the authors report the selective removal of TRBV9+T cells in individuals with ankylosing spondylitis." (PMID 41373714, 2025). "The first anti-TRBV9 treatment of an ankylosing spondylitis patient was successful, resulting in >5-year CR." (PMID 40416957, 2025). "In a related study investigating the treatment of ankylosing spondylitis, a research group identified CD8+T cells expressing TRBV9 as being associated with the pathogenesis of ankylosing spondylitis, psoriatic arthritis, and acute anterior uveitis." (PMID 41373714, 2025). "Targeted depletion of TRBV9+ T cells induces remission in a single patient with ankylosing spondylitis, with significant improvements in functional and mobility metrics." (PMID 37872223, 2023). "This intervention was successful and led to a long-term complete remission of symptoms that were not responding to existing therapeutic interventions, showing feasibility, tolerability and efficacy of antibody-mediated TRBV9+ T cell depletion for the treatment of ankylosing spondylitis." (PMID 37872223, 2023). "Notably, in this period, we observed a decreased frequency of ankylosing spondylitis-associated CDR3 motif in peripheral blood, according to both bulk TCRβ repertoire profiling and deep targeted TRBV9 repertoire profiling (green arrow)." (PMID 37872223, 2023). "Following successful testing in nonhuman primate models, here we report human TRBV9+ T cell elimination in ankylosing spondylitis." (PMID 37872223, 2023).
autoimmune disease (1 paper, 2023). A disorder resulting from loss of function or tissue destruction of an organ or multiple organs, arising from humoral or cellular immune responses of the individual to their own tissue constituents. "We reasoned that the selective deletion of T cells carrying TRBV9+ TCRs using a cytotoxic anti-TRBV9 antibody might provide a safe and effective therapy for HLA-B*27-associated autoimmune diseases." (PMID 37872223, 2023).
breast tumor (1 paper, 2020). "The TRBV9-1, TRBV25-1, and TRBV28-1 genes of CDR3 repertoires in Mouse 1 breast tumor tissue and lung metastatic tissue were lost; and the TRBV9-1 gene of CDR3 repertoires in Mouse 2 breast tumor tissue and lung metastatic tissue was lost." (PMID 33029539, 2020).
celiac disease (1 paper, 2013). An autoimmune genetic disorder with an unknown pattern of inheritance that primarily affects the digestive tract. "This diversity is observed in a total of 19 positions and 22 genes, including the TRBV9 gene, which is implicated in celiac disease." (PMID 23691517, 2013).
melanoma (1 paper, 2009). A malignant, usually aggressive tumor composed of atypical, neoplastic melanocytes. "Conversely, other authors reported that the recognition of melanoma Ags involved the use of T lymphocytes bearing specific TRBV chains, such TRBV5, TRBV9, TRBV19, TRBV27, and TRBV28." (PMID 19317896, 2009).
spondyloarthropathies (1 paper, 2023). "The anti-TRBV9 therapy could potentially be applicable to other HLA-B*27-associated spondyloarthropathies." (PMID 37872223, 2023).
tumor (2 papers, 2018 to 2020). "Here we show that the structures of two distinct TCRs (TRAV4+TRAJ21+-TRBV28+TRBJ2-3+ and TRAV4+TRAJ8+-TRBV9+TRBJ2-1+), originating from a polyclonal T-cell repertoire, bind to HLA-B*07:02, presenting a 13-amino-acid-long tumour-associated peptide, NY-ESO-160–72." (PMID 29531227, 2018).
TRBV9 also shares sentences with these, for which no sentence is quoted: cancer (1 paper); COVID-19 (1); Graves disease (1); Hashimoto thyroiditis (1); juvenile idiopathic arthritis (1); leukemia (1).